MTOR (mechanistic target of rapamycin kinase)
Diseases named in the same sentence as MTOR in open-access papers (continued):
Sharing a sentence is not in itself a finding about the gene and the disease.
tumor (continued). "Since the level of autophagy is grade-dependent in UC, the mTOR activation (autophagy inhibition) may suppress tumor progression." (PMID 35071023, 2021). "Furthermore, recent studies have found a close relation between the activation of the PI3K/Akt/mTOR pathway and the occurrence, development, prognosis, and drug resistance of tumor cells." (PMID 34530814, 2021). "However, a set of chemotherapeutics, as well as, inhibitors of Bcl-2 family, PI3K, HDAC, mTOR and 20S proteasome, yielded a significant decrease in the tumor cell number of GSCs and GdECs." (PMID 34253243, 2021). "In accordance with this biological evidence, targeting mTOR pathways or angiogenesis may reduce glucose uptake by tumor cells, interfering in this way with the proliferation of both these hereditary cancer diseases." (PMID 34207825, 2021). "UBE2O enhanced the malignant behaviors of tumor cells by regulating the AMPKα2/mTOR pathway in HCC." (PMID 34790050, 2021). "Tumor-infiltrating M-MDSCs represent a high level of mTOR phosphorylation." (PMID 35250965, 2021). "Furthermore, mTOR inhibition combined with lapatinib leads to higher synergistic tumor response rates in trastuzumab-resistant xenografts." (PMID 33790792, 2021). "HER3 acts as a key upstream activator of mTOR, we asked whether blockade of HER3 is sufficient to influence mTOR activity and its tumor promoting effects in HNSCC." (PMID 33888713, 2021). "Therefore, the inhibitory effects of mTOR signaling on tumor radioresistance induced by the interaction between macrophages and tumor cells were investigated in the B16F10-derived microenvironment during γ-irradiation." (PMID 33959512, 2021). "In support of the dual action of mTOR inhibition the rapalog everolimus could simultaneously promote expansion of T-regs and activate tumour-specific Th1 immunity." (PMID 34960140, 2021). "Metformin is being investigated because its antineoplastic effects through AMPK-mediated or AMPK-independent inhibition of mTOR; it reduces cyclin D1 inhibiting cancer cell proliferation; it also inhibits tumor cell migration and invasion by inhibiting matrix metalloproteinase-9 (MMP-9) expression." (PMID 33807260, 2021). "A recent study reported that PD‐1 participates in the mTOR pathway in PD‐1‐positive tumour cells." (PMID 32937024, 2021). "Furthermore, increased activity of PI3K/AKT/mTOR signaling pathways in GBM is highly correlated with tumor progression, multidrug resistance, and poor prognosis." (PMID 34831287, 2021). "Importantly, mTOR is the main negative regulator of tumor cell autophagy, which can be activated by Ras-Raf-1-MEK1/2-ERK1/2 and PI3KCI-Akt signaling pathways, while inhibited by kinase B1 (LKB1)-AMP-activated protein kinase (AMPK) pathway." (PMID 34512368, 2021). "Interestingly, we observed that GBM-N019 synergized with palbociclib and significantly delayed tumor growth with concomitant suppression of p-mTOR, mTORC1, mTORC2, Akt, NF-κB, STAT3, and CDK6 when compared to individual therapies." (PMID 34572040, 2021). "Several agents have been identified as an mTOR inhibitor to suppress the tumor." (PMID 33777154, 2021). "Targeted inhibition of mTOR cascade, on the other hand, could produce significant anti-tumor activity in NSCLC cells." (PMID 34326320, 2021). "Overall, these results suggest that inhibition of mTOR signaling in tumor cells may promote their sensitivity to γ-ray-induced ROS." (PMID 33959512, 2021). "In addition, the mTOR signaling pathway promotes cell proliferation and metabolism, both of which contribute to tumor initiation and progression." (PMID 34361836, 2021).
tumor (continued). "Notably, earlier drug studies in RT2 mice targeting c-Myc, VEGFA, and PI3K/Akt/mTOR signaling, yielded similar phenotypes of reduced tumor progression and angiogenesis as seen in RT2; R6KO animals." (PMID 34199469, 2021). "It has been shown that LAT1 contributes to tumor growth by activating mTOR signaling." (PMID 34780467, 2021). "Abnormal changes in the genes may result in abnormal PTEN-PIK3/AKT/mTOR signaling pathways, which can lead to tumor development." (PMID 34565373, 2021). "Several PI3K/AKT/mTOR pathway inhibitors have been studied, with disappointing anti-tumor activity." (PMID 34631559, 2021). "uncovered the higher ITGB2 expression in CAFs promote tumor proliferation in OSCC by activating the PI3K/AKT/mTOR pathways and NADH oxidation in the mitochondrial oxidative phosphorylation system, and ITGB2 was found to be involved in the proliferation, migration, and invasion of CRC cells." (PMID 34926275, 2021). "Rapamycin, an mTOR inhibitor, would inhibit the proliferation of T cells and NK cells, and the maturation and differentiation of DC cells and macrophages, thus impairing the anti-tumor immunoregulation." (PMID 34040054, 2021). "In univariate analysis, high grade, large tumor, advanced stage, metastasis, and high p-mTOR expression were recognized as prognostic factors of poorer CSS, and multivariate survival analysis elucidated that tumor stage, p-mTOR and metastasis were of prognostic value for CSS in ccRCC patients." (PMID 34458019, 2021). "In addition, some studies have shown that mTOR can affect autophagy and apoptosis in tumor cells through various pathways." (PMID 34221974, 2021). "The PI3K/Akt/mTOR pathway is overexpressed in nearly 50% of HCCs and the dysregulated activation of this pathway affects a wide range of processes, including cell proliferation, metabolism, tumor cell differentiation, lipid metabolism, autophagy, and EMT." (PMID 34829868, 2021). "Moreover, activation of PI3K/AKT/mTOR signaling makes a tumor more aggressive in terms of proliferation, angiogenesis, metastasis, and drug resistance." (PMID 34012039, 2021). "However, in other contexts, such as tumor growth, there is coexistence between mTOR and autophagy activation." (PMID 34912234, 2021). "Interestingly, activation of the PI3K/AKT/mTOR pathway is involved in resistance to Shh inhibitors and in proliferation and survival of tumor stem cells, thus contributing to the very poor prognosis of the high-risk patients." (PMID 34395258, 2021). "Additionally, negative feedback loops, alternative pathway activation, and tumor heterogeneity were found to be related to mTOR resistance." (PMID 33107222, 2021). "Among the subtype-1 tumours, we found significant enrichment for the mTOR signalling pathway." (PMID 34506537, 2021). "Many studies on mTOR hyperactivity and its correlation with prognosis have been published; however, mTORC1 and mTORC2 complex distribution and additional metabolic regulatory proteins and their correlation with tumor progression have been less studied." (PMID 35029792, 2021). "It has been shown that conditioning of T cells with MDSCs leads to reduced mTOR activity in T cells as well as increased adoptive T cell-based immunotherapy (ACT) anti-tumor efficacy, suggesting the critical role of MDSCs in mTOR-mediated CD8+ T cells differentiation into effector populations." (PMID 35250965, 2021). "We hypothesized that the AKT activation by MAEL can be resulted in VEGF activation via the mTOR and HIF1a which probably enhanced the angiogenesis and tumor size in GC patients." (PMID 33902648, 2021).
tumor (continued). "A study has also found that miR-101 can inhibit cell proliferation and promote cell apoptosis by regulating the phosphorylation of key proteins PI3K, PTEN, AKT, and mTOR in the Akt/mTOR pathway, which indicated that miR-101 is the gene that can inhibit tumor development." (PMID 34658308, 2021). "Moreover, aberrant activation of mTOR signaling has been implicated in HCC, and HEIH silence exhibited inhibitory effects on the activation of mTOR signaling, leading to decelerate tumor growth and increase survival." (PMID 34689775, 2021). "In our previous clinical study, we found that lipid-rich lesions could be found in most TSC-RAMLs, and TSC-RAMLs with more lipid-rich lesions showed less tumor reduction in response to mTOR inhibitor treatment." (PMID 34243823, 2021). "Of the seven drugs, a multitude of their targeted pathways were associated with tumor cell prolifiation, such as, cell cycle, chromatin histone acetylation, PI3K/MTOR signaling, mitosis, and kinases, which were the latent targets of patients in the high-risk group." (PMID 34568069, 2021). "For example, the serine/threonine kinase mTOR plays an important role in early metastasis through overexpression of its component Rictor, which involves tumor angiogenesis, recruitment of microglia, and apoptosis of Jurkat T cells and primary T cells in the tumor microenvironment." (PMID 34504845, 2021). "Taken together, these results strongly demonstrate a synergistic effect at this dose and indicate that the VEGF inhibitor, bevacizumab (Avastin®) and the mTOR inhibitor, temsirolimus (Torisel®), are exponentially effective at blocking tumor vascularization in combination." (PMID 34077449, 2021). "Commonly, neoadjuvant PI3K/mTOR/AKT inhibition reduces tumor growth." (PMID 34681840, 2021). "Moreover, the phosphorylation, as well as activation of ERK1/2, PRAS40, STAT3 and mTOR, which are well-documented signaling pathways playing important role in apoptosis resistance and tumor progression, was significantly alleviated in shPOLQ cells." (PMID 34517891, 2021). "Indeed, PI3K/AKT/mTOR pathway is the major key regulator of PD-L1 and, when aberrantly up-regulated, it stimulates tumor cell growth and proliferation." (PMID 34209830, 2021). "In future studies, it is necessary to further clarify the mechanism of action of the mTOR pathway in different tumor cells and corresponding immune cells, and evaluate the overall therapeutic effect of mTOR inhibitors, so that it can be better used in tumor treatment." (PMID 33546704, 2021). "Importantly, overexpression of TFG rescued both the tumor‐suppressive effect and inhibition of the TGF‐β and AKT/mTOR pathways caused by CLTC down‐regulation, which indicated that the activity of CLTC was TFG‐dependent." (PMID 34185412, 2021). "The erlotinib and metformin combination also enhanced AMPK-dependent phosphorylation of acetyl-coA carboxylase (ACC), a major downstream effector of AMPK in lipid metabolism, and attenuated mTOR-mediated 4EBP1 phosphorylation and Ki67 cell proliferation marker in the tumor tissues." (PMID 33335306, 2021). "Our results suggested that MHY1485 enhances the radiosensitivity of tumor cells by a mechanism that may differ from MHY1485’s role in mTOR activation." (PMID 34265852, 2021). "Blocking the ERK and PI3K/Akt/mTOR/p70S6K signaling pathways, which result in angiogenesis and tumor growth inhibition, could be utilized as a possible method." (PMID 34768930, 2021). "Another study based on BCa cells indicated that inhibition of GP130 could enhance the sensitivity to GEM and reduce viability and migration of tumor cells through regulating the PI3K/AKT/mTOR signaling pathways." (PMID 35127724, 2021). "Excessive activation of mTOR promotes the development of tumors, and affects the immune regulation involved in the differentiation of immune cells, and plays an important role in tumor metabolism." (PMID 34660693, 2021).
tumor (continued). "Consequently, mTOR hyperactivity and its outcome on a cellular level can influence the therapeutic sensitivity and progression (in a tumor type–dependent manner)." (PMID 35029792, 2021). "High expression of p-mTOR may drive tumor proliferation in almost one third of TNBC, and the p-mTOR positivity is associated with AR expression." (PMID 33915941, 2021). "Furthermore, the results of studies have confirmed the interaction of telomerase/TERT with PI3K/AKT/mTOR and Wnt/β-catenin in various cancers which predominately participating in tumor invasion and metastasis and epithelial to mesenchymal transition (EMT)." (PMID 33869033, 2021). "Altogether, these results conclude that ARHGAP25 acts as a tumor suppressor by inhibiting the AKT/mTOR signaling pathway, which might provide a therapeutic target for PAAD." (PMID 33994864, 2021). "This may in turn change the activity of the mammalian target of rapamycin (mTOR) pathway, which could theoretically result in tumor cell proliferation and metastasis formation." (PMID 34778040, 2021). "Synergistic effects might be possible, as e.g., upregulation of CCK2R with consecutively improved tumor uptake after pre-treatment with the mTOR inhibitor Everolimus was reported in a preclinical study." (PMID 34830930, 2021). "The genome analysis in HPV positive HNSSC tumor showed mutations in PI3KCA gene leading to an increase in mTOR activity rather than Akt phosphorylation and hence helps explains the better efficacy of dual inhibitors against PI3K/mTOR." (PMID 34490084, 2021). "According to previous reports, the mTOR signaling pathway could integrate both intracellular and extracellular signals and function as a central pathway in tumor initiation and progression." (PMID 34581026, 2021). "Overall, the suppression of mTOR signaling in the tumor microenvironment might be useful for the improvement of tumor radioresistance." (PMID 33959512, 2021). "The PI3K/Akt/mTOR signaling pathways have important roles in regulating many aspects of cell growth and survival, being heavily interconnected with many other pathways; that is why these paths have a crucial role in oncogenesis and tumor biology." (PMID 33451055, 2021). "In addition, SLC1A5 silencing in hepatocellular carcinoma can prevent tumor growth and expansion by inhibiting mTOR signal transmission during the translation process." (PMID 34503536, 2021). "Interestingly, Tempus performed on the index tumor had suggested mTOR as a possible therapeutic target, even though prior clinical trials of everolimus in GBM have shown no significant increase in survival." (PMID 34943910, 2021). "In addition, attenuation of LDH-B expression in tumour cells injected into nude mice reduced cell metastasis, in part through reduced activity of the oncogenic mTOR pathway." (PMID 34744727, 2021). "We examined gene expression levels of both JAK/STAT as well as mTOR in this tumor panel." (PMID 34943910, 2021). "Indeed, of the tested tumor models, the zotatifin-sensitive models were those with higher “mTOR activity” scores and higher basal levels of nascent protein synthesis." (PMID 34900714, 2021). "Furthermore, hypoxia invokes excessive mitochondrial fission in liver tumor-infiltrating NK cells, while enhancing mTOR-Drp1 signaling and decreasing the anti-tumor activity of NK cells." (PMID 34868997, 2021). "OGFRP1 promotes tumor progression through activating the AKT/mTOR pathway." (PMID 33744848, 2021). "PCACP significantly inhibited HCC cell proliferation and tumor growth by targeting mTOR (mechanistic target of rapamycin), PAK4 (p21-Activated kinase 4), RHOC (Rho-related GTP-binding protein) and epithelial mesenchymal transition (EMT) pathways both in vitro and in vivo." (PMID 34072348, 2021).
tumor (continued). "Regarding the female dogs, we sequenced 79 BC-related genes, and those with high number of variants shared by tumor fragments and plasma were GATA3 and mTOR (missense), SFRP1 (frameshift insertion), BRCA2 (multi hit), FOXC2, ATM, TGFBR3, and BRIP1 (missense and multi hit mutations)." (PMID 34680380, 2021). "Given the increased levels of IGF-1 and the strongly activated PI3K/Akt-mTOR pathway observed in OS, CR could potentially be effective against this tumor." (PMID 34715874, 2021). "Additionally, the protein expression of phosphorylated mTOR was higher in AW when compared to the WW groups (AW > WW), also presenting a significant effect by age and tumour factors." (PMID 34940589, 2021). "Using the MCF-7/Survivin cell line created with the CRISPR/Cas9 genome editing technology, we proved that Survivin might mediate tumor cell’s MDR via the PI3K/Akt/mTOR pathway." (PMID 35047507, 2021). "Upon disease progression, we used a targeted systemic approach based on the whole genomic profile of the primary tumor, which showed PTEN loss, which is predictive of a benefit from an mTOR inhibitor, and a CCND1 amplification, which predicts sensitivity to CDK4/6 inhibitors." (PMID 34829431, 2021). "Rapamycin combination with many different drugs could have such increased mTOR inhibitory and anti-tumour effects stimulating different types of cell death mechanisms." (PMID 34360785, 2021). "This is in line with a similar study showing that PD-1 could be expressed in tumor cells and could activate mTOR or Hippo signaling pathway, therefore facilitating tumor proliferation." (PMID 34764257, 2021). "In conclusion, the current study indicated that upregulation of EIF4G1 could activate the mTOR signalling pathway, thereby promote the tumour progression in NSCLC." (PMID 33523588, 2021). "Deregulation of the mTOR signaling pathway is also involved in tumor etiology and progression." (PMID 33946531, 2021). "In this study we use NetICS, a computational method to integrate multi-omic data (somatic mutations, miRNA differential expression, transcriptomics, proteomics and phospho proteomics) from an mTOR-driven mouse HCC tumor model, to understand the molecular mechanisms of mTOR-driven HCC." (PMID 34348664, 2021). "In addition, mTOR promotes tumor angiogenesis and regulates the expression of hypoxia-inducible factors that play an important role in a subset of RCC." (PMID 33791295, 2021). "Hyperactivation of mTOR could promote the cell growth and metabolism that lead to tumor progression." (PMID 34513919, 2021). "Moreover, the Western blot results confirmed that the knockdown of BCAT1 reversed the cisplatin-induced decrease in the mTOR phosphorylation level and increase in autophagy in tumor tissues." (PMID 33568627, 2021). "In addition, dual PI3K/mTOR inhibition has shown promising results in treating OS and this anti-tumor activity can be enhanced by MEK/Erk inhibition." (PMID 33467481, 2021). "PRMT5 may act as a tumor inducer in esophageal squamous cell carcinoma by regulating the LKB1/AMPK/mTOR signaling pathway." (PMID 34513846, 2021). "PD-L1 blockade impacts on tumor glycolytic pathway by inhibiting the PI3K/mTOR signaling and decreasing the expression of GLUT1, with a subsequently increased availability of glucose in the TME, favoring the metabolism of activated T cells and restoring IFNγ production." (PMID 33923299, 2021). "Patients with PTEN-deficient tumours could benefit from downstream inhibition of the PI3K pathway, maybe at the level of the mammalian target of rapamycin (mTOR), with EGFR inhibitors." (PMID 33680090, 2021). "Therefore, it is possible that the CE and AKT/mTOR pathway forms a positive feedback loop, reinforcing each other in tumor cells." (PMID 34201030, 2021). "NENs, including LNENs, have been shown to have alterations in signal transduction pathways, such as the PI3K/Akt/mTOR pathway, which may promote tumor growth, along with increased tissue invasiveness and angiogenesis." (PMID 34944946, 2021).